CXCL16 (C-X-C motif chemokine ligand 16)
Diseases named in the same sentence as CXCL16 in open-access papers (continued):
Sharing a sentence is not in itself a finding about the gene and the disease.
cancer (continued). "Collectively, these findings indicate that circulating CCR6 and CXCR6-expressing MAIT cells can be easily attracted into the cancer tissues releasing the corresponding chemokines, such as CCL20 and CXCL16, respectively, in MAC patients." (PMID 27517754, 2016). "The expression of CXCL16 and CXCR6 has been investigated in a variety of human cancers and correlated with both improved and reduced survival." (PMID 26021984, 2015). "CXCL16 was expressed in both stromal and cancer cells, whereas CXCR6 was only expressed in cancer cells." (PMID 26021984, 2015). "High soluble CXCL16 (sCXCL16) levels, result of shedding activities like that of ADAM-10, led us to study impact of sCXCL16 on the two cell types with respect to cancer progression." (PMID 25888629, 2015). "In addition, since CXCL16 exists both as a transmembrane form and a soluble form, and the former could be cleavaged off into the soluble form, it is difficult to distinguish precisely which form is being studied in which cancer experiments." (PMID 24864132, 2014). "Then the enzyme-linked immunosorbent assay (ELISA) and flow cytometry were conducted to examine the functional expression of CXCL16 and CXCR6 in three cancer cell lines." (PMID 24897301, 2014). "However, the role of transmembrane or cellular CXCL16 in cancer remains relatively unknown." (PMID 24864132, 2014). "The receptor for CXCL16, CXCR6, is expressed by several cell types, most notably memory and activated T cells, cancer cells, and ECs." (PMID 21303517, 2011). "Immunofluorescent staining revealed that both CXCL16 and CXCR6 are expressed on CD3+ cells adjacent to cancer cells." (PMID 19690611, 2009). "We also showed that T cells adjacent to cancer cells express CXCL16/CXCR6, that CXCL16 is produced preferentially by CD4+CXCR6+ T cells, and that CXCL16 can enhance the proliferation of T cells." (PMID 19690611, 2009). "Infiltrating immune cells showed active CXCL16 and CCL20 signalling, which aid cancer progression." (PMID 39149248, 2024). "For the comparison of all UCa patients vs. those with other cancers and no cancer at all, we obtained an AUC of 0.77 (95% CI 0.71–0.83) for CXCL16 and an AUC of 0.77 (95% CI 0.71–0.84) for TGFBI." (PMID 39587670, 2024). "In addition to CXCL12, there are other chemokines that hold promise for regulating the migration of cancer cells, such as CXCL8, CXCL16, CCL2, and CXCL10." (PMID 39715221, 2024). "We conclude that LGR6 mRNA analysis of LNs from CC patients can serve as an important complement to CEA- or CXCL16 mRNA analysis detecting cancer stem cells which express very low levels or no mRNA for these two markers." (PMID 38715790, 2024). "Notably, these microbiota-associated dysregulations of BAs have been correlated to immune-related alterations in the liver, for example, downregulation of the Chemokine (C-X-C motif) ligand 16 (CXCL16), a chemotactic cytokine with a peculiar role in cancer." (PMID 38396870, 2024). "Conversely, CXCL16 and IL-15 expressing CCR7+ DCs may recruit and sustain CXCR6+ cytotoxic T cells crucial in cancer immunosurveillance." (PMID 38267413, 2024). "Cxcl16 and Lgals3 were related to Cancer-B1/2/3-TME, while Retnla was related to Cancer-B4-TME." (PMID 39695088, 2024). "On the other hand, the changes between M0 and S + M0 were detected for chemokines CXCL12 (from 0.09 to 0.06 ng/mL, p = 0.0102), CXCL16 (from 0.58 to 0.45 ng/mL, p = 0.0012), and CCL22 (from 0.37 to 0.11 ng/mL, p = 0.0037), demonstrating the inhibitory effect of the cancer cell spheroids." (PMID 37445941, 2023). "In most malignant tumors, the KIFscore was negatively correlated with CXCL16 and CCL14, suggesting that high KIFscores are not conducive to CTL responses against tumors." (PMID 37711200, 2023). "In particular, chemokines, including CXCL8, CXCL10, CXCL11, CXCL16, CCL26, and CCL7, as well as chemokine receptors, including CXCR3, CCR2, CCR5, and CCR1, were positively correlated with MRPL13 expression in various cancer types." (PMID 37827692, 2023).
cancer (continued). "In cancer patients, number of TAM-expressed SRs (CD204, MARCO, CD68, LOX-1, Dectin-1, CD206, CXCL16, Stabilin-1, CD163, and RAGE) associates with negative and more sever prognosis." (PMID 36686729, 2022). "In addition, CXCL16 and CXCL17 have been reported to be positively correlated with M2-macrophage infiltration, enhanced angiogenesis, and poor prognosis in cancer." (PMID 34459571, 2021). "In spite of the evidence in these studies supporting the regulatory function of macrophages on CXCR6 expression in cancer cells, the information on the function and the regulatory mechanism of CXCL16/CXCR6 in adipocytes is lacking." (PMID 34943917, 2021). "The expression of CXCL16 and/or CXCR6 has been shown to be positively correlated with poor prognosis-related factors, such as a higher TNM staging or lymph node metastasis in human cancers including prostate, breast, lung, and thyroid cancers." (PMID 31527616, 2019). "Our study also suggests that CXCL16 is a promising high-grade UC marker, independent of UC history because AUC for high-grade UC in both primary and recurrent cancers was high (AUC 0.875 – 0.783) compared to the hospital controls." (PMID 29285224, 2017). "We observed significantly higher CXCL16 values in non-muscle invasive (≤pT1) low-grade (Δ=0.95, 95% CI 0.59 −1.31) and non-muscle invasive high-grade carcinoma patients (Δ =1.09, 95% CI 0.56 – 1.62) compared to the population controls (p≤0.001)." (PMID 29285224, 2017). "Some cancer cells have high levels of transmembrane ligands called CXCL16 and CX3CL1 but do not produce the corresponding receptors for these molecules." (PMID 26796342, 2016). "CXCL16 is expressed in various cancers, including pancreatic, prostate, breast, colorectal, and nonsmall cell lung cancer." (PMID 24864132, 2014). "Because TOV-21G cells highly express CXCL12/CXCR4 and CXCL16/CXCR6 axes in spite of a low response to EGF or TNF, these axes may contribute to cancer progression as described by others." (PMID 23800251, 2013). "Several additional papers have recently appeared investigating CXCL16 and/or CXCR6 in cancer." (PMID 19690611, 2009). "In addition, we found significant correlations between the presence of reactive stroma and high-level expression of CXCL16 and CXCR6 in cancer cells." (PMID 19690611, 2009). "We considered whether CXCL16 and CXCR6 might function in an autocrine fashion to enhance T cell proliferation analogous to effects on cancer cells." (PMID 19690611, 2009). "Our study is the first to describe the expression of CXCL16/CXCR6 on both cancer cells and adjacent T cells in humans, and to demonstrate correlations between CXCL16 and CXCR6 vs. poor both prognostic features and reactive changes in cancer stoma." (PMID 19690611, 2009). "Taken together, our data suggest that CXCL16 and CXCR6, expressed by both inflammatory cells and cancer cells in human cancers, may be components of inter-related paracrine and autocrine positive feedback loops involving these cells, pleiotropic cytokines and chemokines." (PMID 19690611, 2009). "However, increased expression of CXCL16 does not occur in all types of cancer." (PMID 33800554, 2021). "Of the controls (20 patients without a diagnosis of cancer), 50 % showed varying degrees of positivity for CXCR6 while 100 % showed strong positivity for CXCL16." (PMID 26021984, 2015). "Immunohistochemical analysis of prostate tissue showed low or no staining for CXCL16 and low staining for its receptor, CXCR6 in normal human prostate epithelium, but prominent expression in the cancer." (PMID 19690611, 2009). "Cancer cell CXCR6 and CXCL16 did not have significant impact on survival in univariate analyses." (PMID 26021984, 2015). "Furthermore, the cell retention of cytotoxic T cells on CXCL16 expressing tumors through the main function of the receptor in adhesion, which is not altered by the unusual DRF motif, could dampen cancer growth and metastasis." (PMID 28267793, 2017).
infection (43 papers, 2010 to 2025). The state of being infected such as from the introduction of a foreign agent such as serum, vaccine, antigenic substance or organism. "It is highly recommended that colts that carry the susceptible genotype (CXCL16 S/S or CXCL16S/r) are vaccinated against EAV after 6 months of age to prevent the establishment of LTPI carriers following possible natural infection with EAV." (PMID 35495124, 2022). "Here, we report that infection by Trypanosoma brucei induced depletion of macrophages in the liver, leading to the repopulation of CXCL16-secreting intrahepatic macrophages, associated with substantial accumulation of CXCR6+CD4+ T cells in the liver." (PMID 34614031, 2021). "Interestingly, in one cohort study, the presence of antibodies against specific chemokines (CCL21, CXCL13 and CXCL16) was negatively associated with the development of LC at 1-year post-infection." (PMID 37445634, 2023). "CXCL16 mRNA was unchanged in the kidney following infection and CXCL16 protein expression was detectable throughout the kidney epithelium both in sham- and MuPyV-infected mice by immunofluorescence." (PMID 40043065, 2025). "It has previously been shown that CXCR6 expression is important for T cell migration and localization within the lungs and liver after infection, and that CXCL16 expression by epithelial cells directs this migration." (PMID 37662932, 2023). "Studies on immune surveillance in organs such as the liver and lungs have shown that the chemokine receptor CXCR6 and its ligand CXCL16 are important for migration of CD8 T cells in the tissue during an infection in mice." (PMID 37662932, 2023). "Here we found that infection of EBV in PBMCs caused substantial downregulation of several chemokines, including CXCL16, CXCL8 and SIPR5 all of which play roles as mediators of the inflammatory response to many viruses." (PMID 36272970, 2022). "Spp1–integrins/Cd44 were present only in the 6-month samples, and Cxcl4–Cxcr3 and Entpd–Adora2a were present only in the 3-month samples, while Cxcl16–Cxcr6 expression gradually decreased between T cells and endothelial cells as infection progressed." (PMID 36569953, 2022). "To test this, we administered neutralizing anti-murine CXCL16 antibodies (Ab) during peak infection." (PMID 36153630, 2022). "Overall, modestly downregulated genes in the human BSC were genes involved in chemotaxis and recruitment of infiltrating leukocytes (CCL3, CXCL16) suggesting that RABV suppresses recruitment of infiltrating immune cells to the site of infection." (PMID 34804996, 2021). "For this evaluation, human and murine CNS cell types were infected with Tha (MOI 5) and stimulated at 24 hours post-infection with a hybrid IFN-α which crosses the species barrier to induce CXCL16 expression." (PMID 34804996, 2021). "To this end, we gave WT mice a sublethal LVS IN infection and CXCL16 levels were assessed in the lungs over time." (PMID 32849637, 2020). "The overexpression of miR-145 in macrophages upon Mtb infection can suppress cell viability and infection-induced inflammation via regulating CXCL16, indicating the potential of miR-145 as a therapeutic target of TB." (PMID 32614357, 2020). "The levels of CXCL16 significantly increased as early as 4 days after LVS IN infection and peaked 7–10 days post-infection (an approximately five-fold increase as compared to naïve mice on day 10; P < 0.001)." (PMID 32849637, 2020). "Our own data identified CXCL16 as being up-regulated in the lungs during LVS infection and remained significantly elevated even after the bacterial CFUs had fully cleared." (PMID 32849637, 2020). "Accordingly, expression of Cxcl9, Cxcl10, and Cxcl16 was increased earlier, at 14 days after infection in lungs of C57BL/6 compared with C3HeB/FeJ mice, with expression most pronounced in macrophages, conventional dendritic cells (cDCs), and, in the case of Cxcl10, neutrophils." (PMID 40986319, 2025).
infection (continued). "Similarly, ORFV NA1/11 infection also increased the levels of CXCL16 in the supernatants of cultured LLC cells." (PMID 35959371, 2022). "Furthermore, the exact mechanism(s) of CXCL16 in infection of equine CD3+ T lymphocytes is yet to be determined." (PMID 27930647, 2016). "In our model, some chemokines reported to be part of the "1st and 2nd waves" of chemokine expression by DC cells, specifically Xcl1, Cxcl9, Cxcl16, Ccl1, Ccl2, Ccl3, Ccl4, Ccl5, Ccl7 and Ccl8 are expressed at increased levels in lung i.n. samples at 3 weeks post-infection." (PMID 20942964, 2010). "Thus, based on both our results and those of others, it seems likely that CXCL16 is highly associated with the development of necrotizing pancreatitis with or without infection." (PMID 29891873, 2018). "ARDS patients with overexpressed IL-6, CXCL16, or IGFBP-4 had significantly longer hospital stay and higher incidence of secondary infection." (PMID 27095254, 2016). "CXCL12 and CXCL16 are expressed by the ependyma and periventricular region irrespective of infection, paralleling the expression of CXCR4 and CXCR6 by brain-infiltrating T cells to regulate their migration to infectious foci to the ventricular barrier." (PMID 40581668, 2025). "The positive correlation with CXCL1, CXCL16, and CCR1 indicated that PGK1 may contribute to the recruitment of immune cells, such as macrophages and T cells, to the site of infection or inflammation." (PMID 39712033, 2024). "Measurement of chemokines in the lung showed several alterations in global IFNLR1-/- mice compared to WT mice both during super-infection and single S. aureus infection, including increased TNFα, CXCL11, CXCL12, and MIP3α and decreased IL-1β, MIP1β, and CXCL16." (PMID 39178311, 2024). "By 21 days after LVS infection, at a time when bacterial CFUs were fully cleared, the CXCL16 levels had diminished but not fully returned to that of naïve mice (P < 0.05)." (PMID 32849637, 2020). "In contrast, expression of CXCR6 (the receptor for CXCL16) mRNA was not affected by Ct infection." (PMID 28515460, 2017). "It is possible that that infection could therefore lead to defective trophoblast invasion due to lack of essential attractant signalling molecules secreted from maternal decidua, such as CXCL12 and CXCL16." (PMID 28515460, 2017). "Although our data showed that CXCR6 was not essential for MAIT cell recruitment during LVS infection, this does not rule out a non-redundant role for the CCR6/CXCL16 axis in MAIT cell accumulation." (PMID 32849637, 2020). "Nevertheless, the only known ligand for CXCR6, CXCL16, is sufficient to drive MAIT cell accumulation in the lungs in the absence of infection when administered in combination with the MAIT cell antigen 5-OP-RU." (PMID 32849637, 2020). "Although our data show that CXCR6 is not required to increase MAIT cell numbers in the lungs during the peak of infection, this does not rule out a redundant role for the CXCR6/CXCL16 axis in MAIT cell accumulation." (PMID 32849637, 2020).
cardiovascular diseases (7 papers, 2017 to 2025). "A previous study revealed that CXCL16, which acts as an independent risk factor, significantly elevates the likelihood of cardiovascular diseases." (PMID 40165931, 2025). "The association of CXCL16 with the development of cardiovascular diseases was a topic for discussion in various studies." (PMID 32676207, 2020). "The CXCL16/CXCR16 axis is crucially involved in the development of cardiovascular disorders." (PMID 33854919, 2020).
kidney disease (7 papers, 2012 to 2025). "Taken together, these findings implicate that CXCL16 plays an important role in the pathogenesis of renal disease." (PMID 24489966, 2014). "This suggests that the elevation of CXCL16 in DN patients may be involved in the pathological progression of kidney disease in T2DM subjects." (PMID 24489966, 2014). "Reports of CXCL16 in the development of inflammation in kidney disease are few." (PMID 24460887, 2014). "The aim of this study was to explore the association of circulating CXCL16 levels with diabetic subjects with and without renal disease." (PMID 24489966, 2014). "Previous studies have indicated that serum CXCL16 levels are significantly higher in active SLE patients with renal disease than in active SLE patients without renal disease." (PMID 24489966, 2014). "Importantly, patients with active renal disease exhibited statistically significantly higher mean levels of creatinine-normalized MCP-1 and VCAM-1, compared with the other SLE patients; in contrast, urine CXCL16 was not as discriminatory." (PMID 22788914, 2012).
bacterial infections (5 papers, 2012 to 2020). "As well reported, CXCL16 is expressed by antigen presenting cells, mostly dendritic cells and macrophages that play several functions involved in the response to bacterial infection." (PMID 32218590, 2020).
neurodegenerative disease (3 papers, 2022 to 2024). A disorder of the central nervous system characterized by gradual and progressive loss of neural tissue and neurologic function. "Notably, our data revealed that microglia and astrocytes are the primary expressors of CXCL16 after HBV treatment, in contrast to the expression of CXCL16 by brain microglia and monocytes in neurodegenerative diseases." (PMID 39386089, 2024). "The CXCL16/CXCR6 chemokine signaling pathway may also be an important target for other neurological and neurodegenerative diseases that are associated with neuroinflammation in the CNS." (PMID 36153630, 2022). "In other words, the CXCL16/CXCR6 pathway between T cells and microglia may be an important target for the treatment of other neurological diseases and neurodegenerative diseases related to neuroinflammation in the central nervous system." (PMID 39440247, 2024).
neurologic disorders (3 papers, 2016 to 2024). "Reports of the involvement of CXCL16 in brain injury are limited; however, this protein has been reported to have potential neuropathological or neuroprotective roles in neurological disorders." (PMID 32804078, 2020). "In conclusion, based upon the results of our comprehensive analysis of HHV-6A infected HA1800 cells, we revealed several genes correlated with neurologic disorders, especially CTSS, PTX3, CHI3L1, Mx1, CXCL16, BIRC3, and BST2 genes." (PMID 27344170, 2016).
cardiac diseases (2 papers, 2021 to 2022). "Considering the central role of miRNAs in heart diseases, we next used the TargetScan and other predicted tools to screen the upstream miRNAs of CXCL16 in MI." (PMID 33637127, 2021).
inflammation (2 papers, 2014 to 2025). Aberrant reaction of the microcirculation characterized by movement of fluid and leukocytes from the blood into extravascular tissues. "In this study, we investigated the pathophysiological role of CXCL16 expressed on dendritic cells in Aspergillus-induced airway inflammation to elucidate the function of CXCL16 in DC priming T-cell inflammation." (PMID 40050290, 2025). "Taken together, these results reveal that CXCL16 is mainly expressed in dendritic cells and that its expression level was increased in Aspergillus-induced airway inflammation." (PMID 40050290, 2025). "According to our results, CXCL16 plays a pro-inflammatory role in Aspergillus-induced airway inflammation, and inhibition of CXCL16 suppresses Th2 inflammation." (PMID 40050290, 2025). "In addition, the adoptive transfer of Aspergillus-pulsed DCs shows the CXCL16+ DCs exerted a promoting role in airway inflammation, the CXCL16− DCs inhibit airway inflammation." (PMID 40050290, 2025). "Targeting CXCL16 might therefore represent a promising novel therapeutic approach for liver inflammation and steatohepatitis." (PMID 25372401, 2014).
hematologic malignancies (1 paper, 2022). "As long as CXCL16 is found in the BM at high levels and CXCL8, the CXCR1, and CXCR2 ligand is significantly elevated in MM, CLL, AML, and MDS patients, the targeting of CXCL16-CXCR6 and IL8-CXCR2/CXCR1 pathways should be studied in depth for hematologic malignancies." (PMID 35990652, 2022).